APC (APC regulator of Wnt signaling pathway)
Diseases named in the same sentence as APC in open-access papers (continued):
Sharing a sentence is not in itself a finding about the gene and the disease.
intestinal tumors (continued). "Hence, APC mutations in FAP patients not only drive intestinal neoplasms but also impair T cell migration, potentially contributing to inefficient antitumor immunity." (PMID 35417240, 2022). "Mice with APC mutations can also spontaneously form intestinal tumors, and ApcMinC/Gpt mice are therefore useful for studying the formation of intestinal tumors." (PMID 33841156, 2021). "APC mutations are frequently found in intestinal tumors patients." (PMID 33767595, 2021). "Thus, Nakata and coworkers showed that NOTCH ligand-dependent signaling is indispensable for stem cell proliferation and niche maintenance of APC-deficient intestinal tumors." (PMID 29652830, 2018). "Mice heterozygous for an adenomatous polyposis coli (APC) mutation and a LRH-1 inactivating mutation developed fewer intestinal tumours than mice harbouring the APC mutation only, and LRH-1 heterozygous mice developed fewer azoxymethane-induced aberrant crypt foci." (PMID 26400164, 2016). "Intestinal tumours of humans and mice usually initiate via hyperactivation of Wnt/beta-catenin signalling, which is often caused by genetic loss of the tumour suppressor APC." (PMID 23408899, 2013). "Next, in order to understand whether the development of KRAS-mutated mouse intestinal tumors is associated with increased neutrophils, we examined the number of neutrophils in peripheral blood, spleen, BM and mLN of APC-WT and APC-KRASG12D mice at different time points." (PMID 32228650, 2020). "Furthermore, it was shown that the expression of the intestinal stem cell markers CD44, CD133 and CD166 was induced in intestinal tumors only of bouble mutant APC defective/KRAS-mutant mice, thus indicating that APC mutation is required for CSC activation by oncogenic mutant KRAS." (PMID 29652830, 2018). "The fact that RASSF1A cooperates with APC loss to promote intestinal tumors suggests that SRC activation may contribute to colorectal tumorigenesis by promoting the tyrosine phosphorylations of both β-catenin and YAP1 that are required for nuclear localization and transcriptional activation." (PMID 26549256, 2015). "The notion of a competition between APC and Dishevelled for their association with Axin is consistent with previous evidence from epistasis experiments in Drosophila embryos and murine intestinal tumours, which indicated that APC acts at the same level as Dishevelled rather than below it." (PMID 22645652, 2011). "This study employs spatial transcriptomics (ST) to investigate the progression of intestinal tumors in APC Min/+ mice across multiple time points." (PMID 41009818, 2025). "APC-mutant intestinal stem cell (ISC) clones cause wild-type ISCs to differentiate, thereby outcompeting them and leading to intestinal tumor initiation." (PMID 39459551, 2024). "The mutation of APC and CTNNB1 leads to excessive activation of Wnt signaling by inducing the stabilization of β-catenin, which initiates intestinal tumors." (PMID 37190019, 2023). "We further investigated the role of Usp7 in CRC using two independent mouse intestinal tumor models (Apcmin and Apchet) that mimic human patients with FAP with germline APC mutations predisposed to CRC development." (PMID 36669491, 2023). "In human CRC tumour tissues, the glutamine concentration was significantly lower in tumours than in healthy tissues, and this phenomenon was also found in intestinal tumours from heterozygous APC mutant mice." (PMID 35869517, 2022). "Above result was further evaluated by Western blot analysis against proteins extracted from intestinal tumors of APCmin/+ mice or those from normal intestine of APC+/+ mice." (PMID 33465122, 2021).
intestinal tumors (continued). "In contrast, BLM transgenic mice expressing human BLM attenuated intestinal tumors when crossed with APC heterozygous mutant mice, thereby indicating that tumor growth can be regulated in a BLM dose-dependent manner." (PMID 33777104, 2021). "To utilize the TiBcs in the tumor of APCmin/+ mice, we isolated B cells from intestinal tumors of APCmin/+ mice and those from normal intestinal tissues of APC+/+ mice for a control." (PMID 33465122, 2021). "The adenomatous polyposis coli (APC) gene product is mutated in the vast majority of human CRC and deletion of the APC gene leads to intestinal tumor formation in mice." (PMID 32850342, 2020). "Several studies have previously shown that changes in APC dosage can affect cellular motility, migration and polarity, and can induce the development of early intestinal neoplasms." (PMID 30024920, 2018). "ERα and ERβ are known modifiers of APC-dependent tumorigenesis, and their inactivation increases intestinal tumor formation in the ApcMin mice." (PMID 29163805, 2017). "Regarding the CXCL12 loss, it results from a promoter acetylation defect for the large majority of carcinomas and treating APC mutant mice with a HDAC inhibitor importantly reduces the intestinal tumor development." (PMID 28418886, 2017). "In vivo, valproate diminished (65%) the number of intestinal tumors in APC mutant mice, slowed down xenograft tumor growth concomitant to restored CXCL12 expression." (PMID 28418886, 2017). "Focusing on a genetically engineered mouse model, cultured spheres derived from APC/KRAS/PTEN intestinal tumours were largely insensitive to BEZ235 as a single agent; however, they responded to sequential treatment with bortezomib followed by BEZ235." (PMID 27897178, 2016). "In these cases, inhibition of PLK1 in colon cells expressing mutant APC-ΔC disrupts spindle assembly checkpoint (SAC) recruitment by reducing the localization of BUBR1 and MAD1 at the centromere, leading to chromosomal abnormalities and an increased number of intestinal tumors in APC Min/+ mice." (PMID 40612941, 2025). "Additionally, xStAx-VHL inhibits the growth of CRC xenografts and APC Min/+-driven intestinal tumors." (PMID 37190019, 2023). "In this study the endpoint, ε, is intestinal tumors in tumor-prone adenomatous-polyposis-coli APC(1638N/+) mice, and the data are tumor yields (number of tumors per mouse) after exposure to space-relevant doses of energetic 1H, 4He, 12C, 16O, 28Si, or 56Fe ions." (PMID 35087104, 2022). "BLM heterozygous mutant mice developed T cell lymphoma at a much more rapid rate when challenged with murine leukemia virus and the frequency of intestinal tumor development is higher when crossed with Adenomatous Polyposis Coli (APC) gene heterozygous mutant mice." (PMID 33777104, 2021). "In addition, SLAP silencing increases intestinal tumour initiation and progression in ApcΔ14/+ transgenic mice that carry a heterozygous mutation of the APC tumour-suppressor gene and consequently develop WNT-pathway-driven intestinal tumours." (PMID 31091767, 2019). "Indeed, a recent report highlighted the central importance of APC in intestinal tumor suppression using a doxycycline-inducible APC shRNA, enabling toggling of wild type APC." (PMID 30131940, 2018). "Nevertheless, VPA could reduce ectopic tumor growth in vivo as well as the number of intestinal tumors in APC mutant mice, and this effect was concomitant to the re-expression of CXCL12." (PMID 28418886, 2017). "Recently, another interesting study reported that restoring the function of the tumor suppressor the adenomatous polyposis coli (APC) causes complete tumor regression with normal differentiation and reestablishes stem cell function in mouse intestinal tumors induced by APC inhibition." (PMID 26739838, 2016).
intestinal tumors (continued). "In this study, using the APCMin/+ intestinal tumor mouse model, we demonstrated downregulation of RXRα expression, which may complement the disabled APC-dependent proteasomal degradation pathway to increase β-catenin accumulation in 56Fe-induced tumors." (PMID 26500891, 2015). "Our study demonstrates that targeted WNT-pathway inactivation may be an effective strategy for treating APC-mutant driven intestinal neoplasms." (PMID 25003333, 2014). "Wide variation in the frequency of LOH of APC gene (31 to 70%) has been observed for human CRC and APCMin/+ mice exposed to whole body 2 Gy x-ray radiation showed loss of the wild type allele (LOH) in about half of the intestinal tumors." (PMID 23555653, 2013). "Mice heterozygous for an adenomatosis polyposis coli (APC) mutation and an LRH-1 inactivating mutation developed fewer intestinal tumours than mice harbouring the APC mutation only, and LRH-1 heterozygous mice developed fewer azoxymethane-induced aberrant crypt foci." (PMID 24049078, 2013). "In Smad2/APC (adenomatous polyposis coli) double heterozygous mice, Smad2 deletion accelerates APC mutation-induced intestinal tumor growth and invasion but does not increase the number of tumors." (PMID 22204491, 2011). "Consequently, activation of the typical Wnt pathway triggered by APC inactivation could result in intestinal tumor occurrence." (PMID 32587775, 2020). "Importantly, these data strongly suggest that the CpG hypo- and hypermethylation patterns of intestinal tumours do not derive from ISCs, but form de-novo and in a recurring manner after tumour initiation following the loss of APC." (PMID 23408899, 2013). "Taking advantage of the fact that patient somatic cells are APC heterozygous, we sought to recapitulate the primordial developmental state of gut epithelia and study the cellular and molecular “milieu” that may provide a bona fide environment for the development of intestinal tumors." (PMID 30024920, 2018). "In intestinal tumours, DCLK1 often co-expresses with LGR5 at crypt base and DCLK1+LGR5+ stem cells are able to continuously produce tumour progeny under the APC+/− mice." (PMID 28195176, 2017). "Since the 10-week old APC∆14/+ mice had spleens of normal size and weight compared to APC+/+ mice, we chose to determine the effect of PAK1 KO on intestinal tumour development and splenic lymphocytes in 10-week old mice." (PMID 28629331, 2017). "Both mutant Tdg x ApcMin mice and the low TDG/low APC patient subset are characterized by an excess of female cases, which indicates that TDG may normally mediate the protective effects of estrogen on intestinal tumor formation." (PMID 29163805, 2017). "Expression of the CSC markers CD44, CD133, and CD166 was induced in intestinal tumours from APC (Min/+)/K-Ras (LA2) mice, but not K-Ras (LA2) mice, indicating that K-Ras mutated cells are more tumorigenic and that APC mutation is required for CSC activation by oncogenic K-Ras mutation." (PMID 36386200, 2022). "However, the status of the APC-independent proteasomal targeting of the β-catenin in heavy ion radiation-induced intestinal tumors has not been explored." (PMID 26500891, 2015).
Lynch syndrome (64 papers, 2008 to 2026). An autosomal dominant hereditary neoplastic syndrome characterized by the development of colorectal carcinoma and a high risk of developing endometrial carcinoma, gastric carcinoma, ovarian carcinoma, renal pelvis carcinoma, and small intestinal carcinoma. "The genes with the highest prevalence of P/PV variants included CHEK2 (26%), MUTYH (21%), BRCA2 (8%), APC I1370K (8%), and Lynch Syndrome-associated (7%)." (PMID 40770526, 2025). "Genetic factors include rare hereditary syndromes such as adenomatous polyposis coli (germline APC mutation) and Lynch syndrome." (PMID 35260534, 2022). "It is well established that early screening for polyps in family members of patients with characterized mutations in MMR (Lynch syndrome), APC (FAP), or MUTYH (MAP) genes is beneficial in improving detection of malignant changes and reduces mortality." (PMID 24550697, 2014). "Examples are the Lynch syndrome, which is characterized by a germline mutation in one of the DNA mismatch repair genes, and the Familiar Adenomatous Polyposis, in which patients carry a mutated adenomatous polyposis coli (APC) gene." (PMID 31052449, 2019). "We analyzed the proportion of MMR-deficient and MMR-proficient crypts showing APC inactivation as a first indicator for the distribution among the three currently hypothesized pathways of carcinogenesis in Lynch syndrome individuals, with a good concordance to current clinical observations." (PMID 34003820, 2021). "For instance, APC mutations often lead to aberrant activation of the Wnt/β-catenin pathway, whereas defects in MMR genes are strongly associated with Lynch syndrome." (PMID 40995229, 2025). "Out of 103 patients who underwent germline testing for Lynch syndrome, 19 (18.4%) showed a mutation in MMR genes with pathogenic or likely pathogenic significance and 8 (7.8%) in other CRC-associated genes (APC, CHEK2, MUTYH)." (PMID 39457591, 2024). "No pathogenic variants were observed in BRCA1, STK11, CDKN2A, APC, PRSS1, or those genes associated with Lynch syndrome." (PMID 39594734, 2024). "In the cluster of co-cited authors, the presentative cluster labels included diet, colonoscopy, traditional serrated adenoma, lynch syndrome, metabolic syndrome, microbiota, APC, cyclooxygenase-2, endoscopic resection and folate." (PMID 37492472, 2023). "Initially, she was suspected to have FAP or Lynch syndrome, but genetic testing revealed no pathogenic variants in APC, MUTYH, or mismatch repair genes." (PMID 40741356, 2025). "After limiting to studies that excluded Lynch syndrome, the associations between early-onset CRC and BRAF (0.77, 0.64-0.92) and APC mutation (0.81, 0.67-0.97) were attenuated, while an inverse association with PIK3CA mutation was also observed (0.88, 0.78-0.99)." (PMID 38737895, 2024). "For patients without Lynch syndrome, APC was identified as the gene associated with the most mutations (n = 14) and was followed by BRCA1 (n = 8), RAD50 (n = 7), MUTYH (n = 5), ATM (n = 5), and BRCA2 (n = 4)." (PMID 35014770, 2022). "The APC gene had the highest number of P germline mutations, thus indicating that FAP is the most common form of hereditary CRC in Chinese population, followed by Lynch syndrome." (PMID 35014770, 2022).